APOE (apolipoprotein E)
Diseases named in the same sentence as APOE in open-access papers (continued):
Sharing a sentence is not in itself a finding about the gene and the disease.
aneurysm (continued). "The radiolabeled RGD positron emission tomography (PET) tracer 18F-FPPRGD2, which also targets integrin αvβ3, was able to detect vascular inflammation in AngII-infused ApoE−/− mice but did not correlate with aneurysm size." (PMID 35492343, 2022). "The rupture rate, number of ruptured aneurysms, vessel thickness and vessel wall area in both the thoracic and abdominal portions of aortae were all significantly reduced in the CCN4−/−ApoE−/− mice compared to CCN4+/+ApoE−/− controls." (PMID 34080128, 2021). "We found that concurrent treatment with pravastatin and aspirin did not reduce tropoelastin accumulation, aneurysm formation or aortic dissection in Ang II-infused ApoE-/- mice." (PMID 31282949, 2020). "Ang-II infusion in ApoE−/− mice induced the formation of suprarenal aneurysm and structural alterations in the whole aorta, whereas no spontaneous AAAs were observed in saline-infused mice." (PMID 26989193, 2016). "We also noted aneurysms at the study end point in surviving ApoE−/− mice, which were absent in Rgs1−/−ApoE−/− mice." (PMID 25782711, 2015). "However, the AngII-induced aneurysm model, in apoE−/−, cathepsin K−/− double KO mice, showed no attenuation of aneurysm formation." (PMID 31546645, 2019). "Between days 3 and 10 of Ang II infusion, 7 out of 16 non-BMT ApoE−/− mice died from aneurysm rupture, but no deaths occurred in BMT mice, indicating that BMT may confer protection from Ang II-induced aortic aneurysm rupture." (PMID 30048944, 2018). "Furthermore, between days 3 and 5 of Ang II infusion, two out of six ApoE−/− mice died from aneurysm rupture, but no deaths occurred in Rgs1−/−ApoE−/− mice, indicating that Rgs1 deficiency confers protection from Ang II-induced aortic aneurysm rupture." (PMID 25782711, 2015). "No aneurysms were present in saline-infused control ApoE−/− mice (n = 12)." (PMID 25431606, 2014). "Recent data suggests that bosentan may augment aneurysm incidence in Ang II-infused ApoE−/− mice, although our data did not support this conclusion." (PMID 23226500, 2012). "In male apoE−/− mice infused with Angiotensin II (a common animal model of AAA), atherosclerotic lesions were only detected after development of the aneurysms suggesting that the link between aneurysm development and atherosclerosis may be opposite than previously thought." (PMID 37476203, 2022). "We also noted a 13% incidence of aneurysms at the study end point in surviving non-BMT ApoE−/− mice, which were absent in BMT ApoE−/− mice." (PMID 30048944, 2018). "Using a pan caspase inhibitor Q-VD-Oph in Angiotensin II (Ang II)-induced AAAs in apolipoprotein E (apoE) knockout mice, we showed that SMC apoptosis is essential for aneurysm formation but not required for aneurysm growth." (PMID 28186202, 2017).
Atrophy (79 papers, 2012 to 2026). Any weakening or degeneration, especially through lack of use. "The current investigation demonstrated the influence of the APOE ɛ4 allele on the progression of Aβ accumulation and GM atrophy, presenting evidence for a distinct spatiotemporal pattern in individuals with memory decline." (PMID 40167963, 2025). "The tau PET clusters and atrophy clusters included more frequently APOE ε4 allele carriers compared to HC." (PMID 40415101, 2025). "Studies investigating the effect of the APOE ε4 allele on the association between atrophy in AD-related brain regions and spatial navigation performance are lacking." (PMID 40456910, 2025). "Associations of APOE genotype and memory decline with Aβ accumulation and GM atrophy were examined separately for each neuroimaging modality, controlling for baseline Aβ levels and diagnosis." (PMID 40167963, 2025). "Apolipoprotein E (ApoE) ε4 allele is the major genetic risk factor for AD and is associated with increased amyloid‐β (Aβ) deposition and accelerated brain atrophy." (PMID 38376028, 2024). "Future studies will be able to test this possibility by covarying amyloid and tau burden when evaluating associations between APOE-ɛ2 status and atrophy." (PMID 39229494, 2024). "This is the first study to document the effects of epistatic interactions between the MTHFR C677T and APOE polymorphisms on GM atrophy in aMCI patients and healthy subjects to the best of our knowledge." (PMID 34916904, 2021). "On the other hand, increased expression of APOE ɛe4 allele affects the flow of cerebral blood, further contributing to atrophy." (PMID 28731430, 2017). "Although vascular risk factors have been consistently linked with smaller regional brain volumes and atrophy rates, little is known about whether APOE variants moderate this relationship." (PMID 39229494, 2024). "We sought to deepen our understanding of the role of susceptible genes such as MTHFR and APOE and the outcome of their interactions on GM atrophy in aMCI disease, which could importantly help to develop new strategies for disease prevention and early therapy." (PMID 34916904, 2021). "However, using partial correlation, and adjusting for APOE, we identified a number of plasma proteins that were significantly associated with atrophy using MRI measures of one or more of the brain regions; hippocampus, entorhinal cortex, ventricles, and whole-brain volume in the disease groups." (PMID 25012867, 2014). "Overall, APOE ε4 status significantly affected naming and memory scores, mesial temporal and entorhinal cortex atrophy scores, and glial fibrillary acidic protein concentration levels." (PMID 41085166, 2025). "We performed a two-way ANCOVA to compare how the APOE genotype and memory decline groups, and the combination of both, affected the GM atrophy." (PMID 40167963, 2025). "With respect to GM atrophy, there are several studies that have used T1-weighted magnetic resonance imaging (MRI) to examine APOE ε4’s effect on GM; however, the results are contradictory." (PMID 40167963, 2025). "Subtypes of atrophy in AD predict an early onset, shorter disease duration, and APOE ε4-positive patients." (PMID 40870510, 2025). "The multimodal analysis detected evidence for a three-way interaction of APOE genotype, memory decline, and longitudinal GM atrophy, which are collectively related to Aβ accumulation in the areas surrounding the fusiform gyrus." (PMID 40167963, 2025). "The primary finding of the present study was the detection of an interaction between the APOE genotype and memory decline on the voxel-wise change rates of both Aβ and GM atrophy." (PMID 40167963, 2025). "Our study allows isolating the contributions from sex, APOE status, and education level on both onset age and pace of atrophy for each region of the cortex and brain, while accounting for the other covariates." (PMID 37333001, 2023).
Atrophy (continued). "Covariance analysis was used to disentangle the effect of sex and APOE genotype on the regional onset age and pace of atrophy, while correcting for educational level." (PMID 37333001, 2023). "These clusters clearly reflect differences in cognitive scores, APOE allele status, PPR parameter β and baseline atrophy patterns." (PMID 34704025, 2021). "Nonetheless, these studies investigated only the interactions between genes at the clinical level, whereas the effects of MTHFR C677T and MTHFR × APOE genotypes interactions on GM atrophy in aMCI were largely unexplored." (PMID 34916904, 2021). "In line with the results from survival analyses, PHS significantly predicted clinical decline of both CDR-SB and MMSE among elderly diagnosed with MCI beyond APOE status, both individually and when atrophy levels were included in the model." (PMID 29760643, 2018). "Baseline demographics, APOE genotypes, Brain Volumes, and 1-Year Rates of Atrophy in PiB-positive and PiB-negative individuals." (PMID 23554933, 2013). "Baseline demographics, APOE genotypes, Brain Volumes, and 1-Year Rates of Atrophy for all individuals included in the study." (PMID 23554933, 2013). "In the results presented in this paper on the effects of CSF α-synuclein on atrophy rates, we adjusted all models for APOE genotype, age and sex." (PMID 24392009, 2013). "Associations were also observed for brain volume atrophy, however these exhibited subgroup variability without clear patterns relative to sex and APOE ε4 allele carriage." (PMID 40221237, 2025). "Instead, allocentric navigation deficits were primarily associated with AD biomarkers and atrophy in AD-related brain regions, regardless of APOE genotype." (PMID 40456910, 2025). "The negative associations of APOE-ɛ4 with atrophy were reduced among those with higher education (P < 0.04) and younger baseline ages (P < 0.03)." (PMID 39229494, 2024). "The associations between regional apoE levels and relative brain volumes, as well as the finding that the relative size of the PFC and amygdala might be spared from radiation-induced atrophy, is of high translational relevance to human health." (PMID 34764354, 2021). "In light of this, it would not be surprising that the correlation between MTHFR polymorphism and GM atrophy in aMCI patients was present only in APOE ε4 non-carriers in our current study." (PMID 34916904, 2021). "By extending previous work on APOE ε4-sex interaction effects on brain tau deposition in cognitively normal and MCI cohorts 12, 24, our study revealed that sex also modifies the effect of APOE ε4 on brain tau deposition and atrophy in individuals with AD using data from the ADNI consortium." (PMID 32929366, 2020). "We also evaluated sex by APOE ε4 interaction effects on brain region-specific atrophy." (PMID 32929366, 2020). "This inconsistency in findings may be explained by the fact that previous studies do not classify MCI groups or control for all of the factors affecting atrophy, including age, sex, level of education, and APOE ε4 genotype." (PMID 31551759, 2019). "Fifth, information of variables including APOE, hippocampal volume or global atrophy or amnestic phenotype was unavailable in this study, which could potentially cause bias." (PMID 31474887, 2019). "Furthermore, 18F-AV-1451 and APOE ε4 status interacted to predict cortical thickness, with stronger effects of 18F-AV-1451 on atrophy in APOE ε4-negative patients." (PMID 30086796, 2018). "APOE ε4-negative patients may be more likely to deposit tau and have more atrophy in the parietal lobes compared with APOE ε4-positive AD, which predispose them to a nonamnestic clinical phenotype." (PMID 30086796, 2018). "Similarly to AD patients, age was associated with a reduction in atrophy rate for MCI patients of 2 mL/y (0.60–3.19) for a 10-year increase in age after adjusting for WMH and APOE e4 and subtracting the age–atrophy effect in controls." (PMID 29220823, 2018).
Atrophy (continued). "Abnormal tau and amyloid β42 cerebrospinal fluid levels, baseline MRI atrophy, and apolipoprotein E ε4 status have been used as successful stratification strategies and should be applied to define an early clinical population, such as MCI, or at-risk asymptomatic subjects." (PMID 29458420, 2018). "As expected, APOE ε4 alleles, MMSE, atrophy score, and PHS were related to subsequent progression." (PMID 29760643, 2018). "−0.20 years) after the mean scenario, contrary to patient without APOE-ε4 alleles that present an average time-shift of 1.89 years, meaning that the more alleles, the earlier the atrophy onset occurs." (PMID 29780348, 2018). "Significant associations with APOE or TOMM40 genotypes may become apparent at this older age, after more age-related atrophy." (PMID 24260406, 2013). "The hippocampus hosts adult neurogenesis and is an important structure for episodic memory, and carriers of the apolipoprotein E ε4 allele exhibit higher hippocampal atrophy rates and differing telomere dynamics compared with non-carriers." (PMID 22506016, 2012). "Altogether, these results fit with a dimensional view of aging, where APOE ε4 and early preclinical change in AD are one of many pathways affecting common biological substrates that determine memory function in older age, namely, regional and global macrostructural atrophy." (PMID 41271752, 2025). "Our sample size did not account for confounding comorbidities such as body mass index, genetic factors such as apolipoprotein E (APOE) genotype, and whole brain and/or regional atrophy, as well as the presence of infarcts." (PMID 40656407, 2025). "As better sleep has been shown to have attenuating effects of the APOE ε4 genotype on AD risk, and sleep–atrophy relations have been found to be partly independent of APOE genotype, we hypothesized the relations to remain when controlling for APOE ε4 status and PGSs for sleep and AD, respectively." (PMID 33912975, 2021). "In this study, we investigated the effect of age on atrophy rate patterns in a large multisite data set of predominantly late-onset MCI and AD patients allowing for normal aging effects, WMH volume, and APOE e4 status." (PMID 29220823, 2018). "APOE-ɛ2 status (ɛ2/ɛ2 and ɛ2/ɛ3 combined) was not related to baseline levels or atrophy in SPARE-AD, SPARE-BA or the hippocampus, but was related to greater increases in white matter hyperintensities (P = 0.014)." (PMID 39229494, 2024). "Subjects with MCI had atrophy rates of 10 mL/year for the whole brain and 0.1 mL/year for the hippocampus, for apolipoprotein E (APOE) negative individuals." (PMID 39210976, 2024). "A lack of genetic data, including APOE status, meant we were unable to assess for an interaction with atrophy." (PMID 36696255, 2023). "Using the t‐test model, only the negative association of the atrophy patterns from the t‐test model and CDR‐SB is observed for the APOE ε4 noncarriers (r = −.165, p = .045)." (PMID 36394351, 2023). "Compared with the previous studies, our study found that some AD subjects showed obvious asymmetrical atrophy in left lateral temporal-parietal cortex, OSAD presented the worst cerebrospinal fluid levels, and MAD had the highest proportions of APOE ε4 and APOE ε2." (PMID 33672406, 2021). "Converging evidence showed a different atrophy pattern between APOE ε4 carriers and ε4 non-carriers." (PMID 31159873, 2019). "Controls had an average atrophy rate of 6 mL/y (5.66–6.72) for the whole brain and 0.06 mL/y (0.05–0.07) for the hippocampus, for APOE negative individuals with the mean TIV and WMH load." (PMID 29220823, 2018). "The model shows that, for instance, APOE carriers have a significantly higher pace of cortical atrophy but not earlier atrophy onset." (PMID 29780348, 2018).
Atrophy (continued). "The current results align with a more hippocampal-centric pattern of atrophy but also fit well with a dimensional view of aging, where APOE ε4 contributes to accelerated brain aging, without changing the macrostructural mechanisms underlying the change – change associations." (PMID 41271752, 2025). "(ii) To investigate whether the APOE ɛ4 effects on ODI are independent of atrophy, we additionally adjusted for mean cortical thickness." (PMID 38384997, 2024). "Indeed, our previous study revealed that BZBS did not prevent uterine atrophy in Ovx/ApoE-/- mice." (PMID 34248622, 2021). "We observed a significant main effect of APOE genotype on GM atrophy in the right hippocampus of aMCI patients, and the right precuneus could be influenced by the interaction between diagnosis and MTHFR C677T genotype in aMCI and HC subjects not carrying the APOE ε4 allele." (PMID 34916904, 2021). "Conversely, APOE-ɛ2 primarily influences WMH accumulation, but not atrophy." (PMID 39229494, 2024). "Baseline demographics, APOE genotype, neuropsychometry, SUVR, brain volumes and annualised rates of atrophy in amyloid positive and negative normal controls from this study compared to ADNI amyloid positive/negative individuals defined on the basis of CSF Aβ1-42." (PMID 23554933, 2013).
Onset (75 papers, 2007 to 2026). The age group in which disease manifestations appear. "Environmental risk factors and apolipoprotein E4 (ApoE4) encoded by the ε4 allele of the APOE gene can contribute to toxic Aβ species-induced tau pathology in late-onset AD." (PMID 41189817, 2025). "Polymorphism in the APOE gene is recognized as a major genetic risk factor for late‐onset AD (LOAD), with the APOE ε4 allele conferring an increased risk." (PMID 39749650, 2025). "When disturbed, it increases the risk of neurological disease, as strikingly demonstrated by the association of the apolipoprotein E (ApoE) allele ε4 (APOE ε4) with late-onset AD." (PMID 41210483, 2025). "Currently, the ε4 allele of APOE (APOE-ε4) is considered the strongest genetic risk factor for autosomal dominant early-onset AD and late-onset AD in a dose-dependent manner, but it was also found to be associated with DLB in GWAS." (PMID 38153678, 2024). "With the discovery in 1993 that the apolipoprotein E type 4 allele (APOE4) was the major risk factor for sporadic, late-onset AD (LOAD), there has been increasing interest in cholesterol in AD since APOE is a major cholesterol transporter." (PMID 36845656, 2023). "Apolipoprotein E4 (APOE4) genotype is the strongest genetic risk factor for late-onset AD and is associated with increased tau burden." (PMID 37600228, 2023). "Among them, APOE, encoding apolipoprotein E, is a major genetic risk factor for late-onset AD and is also associated with CVD and longevity." (PMID 39872551, 2023). "Another crucial gene in astrocytes is APOE, the first risk factor for late-onset AD, which undergoes APA and reduced expression in astrocytes." (PMID 37799732, 2023). "Cholesterol and its links with AD pathogenesis have been studied in depth, with the genetic variant APOE ε4 of apolipoprotein E (ApoE) being the strongest genetic risk factor for late-onset AD (LOAD)." (PMID 34685570, 2021). "ApoE E4 is a recognized risk factor for AD, in contrast to apoE E2, which has a protective effect and significantly reduces the risk of developing late-onset AD." (PMID 34068096, 2021). "The human APOE gene has three alleles: APOE2, APOE3, and APOE4, with APOE2 being associated with the reduced risk for late-onset AD, while APOE4 is a major risk factor for late-onset AD." (PMID 34930382, 2021). "In sporadic AD alteration of ApoE gene is the main risk factor and ε4 allele of APOE gene is highly frequent in late-onset AD (LOAD)." (PMID 32429462, 2020). "Apolipoprotein E (APOE) allele 4 is also established as a high genetic risk for sporadic late-onset AD besides being reported as a risk factor for cardiovascular disease." (PMID 33282526, 2020). "Afterage, the presence of the E4 allele of the gene that codes apolipoprotein E (APOE-ε4)represents the largest risk factor for Aβ accumulation in late-onset AD." (PMID 31073376, 2019). "The expression of APOE, the first and the strongest genetic risk factor for late-onset AD, showed the biggest up-regulation among all AD risk genes with a ~ 8-fold increase in rTg4510 microglia cells at 4 months of age." (PMID 30558641, 2018). "ApoE exists in three isoforms – ApoE2, ApoE3, and ApoE4, and among these three isoforms, ApoE4, is the greatest risk factor for late-onset AD and Aβ-induced neuroinflammation." (PMID 26074758, 2015). "The ApoE ε4 allele is known to contribute to a genetic predisposition for late-onset AD, although the mechanisms by which ApoE ε4 influences onset and progression of the disease are not well understood." (PMID 22523490, 2012). "The genes primarily involved in AD are Amyloid Precursor Protein (APP), Presenilin 1 (PSEN1), and Presenilin 2 (PSEN2), which are associated with early-onset familial AD (fAD), variations in apolipoprotein E (APOE) gene increase the risk of late-onset sporadic AD (sAD)." (PMID 39861466, 2025).